DNMT3A (DNA methyltransferase 3 alpha)
Diseases named in the same sentence as DNMT3A in open-access papers (continued):
Sharing a sentence is not in itself a finding about the gene and the disease.
hematological cancers (15 papers, 2015 to 2025). "Most of DNMT3A mutations found in hematological cancers are located within the methyltransferase domain, with a higher prevalence (about 65%) of heterozygous missense mutations at codon R882." (PMID 32188030, 2020). "It is well known that age-related clonal hematopoiesis is associated with increase in the risk of hematologic cancer and the majority of the variants occurred in three genes: DNMT3A, TET2, and ASXL1." (PMID 29619119, 2018). "TET2 and DNMT3A mutations likely occur early during evolution of hematopoietic neoplasms and are even detectable in apparently healthy individuals." (PMID 29148847, 2018). "Similarly, among DNMT enzymes, DNMT3A represents one of the most frequently mutated genes in diverse types of hematological cancers." (PMID 29069286, 2018). "Moreover, DNMT3A mutations have an adverse prognostic impact in hematologic cancers." (PMID 29721185, 2018). "Mutations in DNMT3A were originally identified in AML patients in 2010 and subsequently in other adult hematological cancers, often arising as early event in AML pathogenesis." (PMID 32188030, 2020). "ARCH/CHIP is mainly associated with mutations in three epigenetic regulatory genes—DNMT3A, TET2, and ASXL1—that have been implicated in hematologic cancers and is a strong risk factor for subsequent hematological cancers." (PMID 33292805, 2020). "Herein, the organization characteristic of DNMT3A and critical implications of DNMT3A alterations in hematological cancers are highlighted." (PMID 28127428, 2017). "Hematological cancers are characterized by recurrent mutations in genes involved in the regulation of DNA methylation, notably TET2, IDH1/2 and DNMT3A." (PMID 25901663, 2015). "Likewise, our data reported here confirm that indeed, Flt3ITD/+ and bone marrow specific Dnmt3a deletion cooperate to result in shortened survival due to the development of fatal hematopoietic neoplasms, including AML and T-ALL." (PMID 27636998, 2016).
blood cancer (13 papers, 2019 to 2025). "It is important to emphasize that the development of cardiovascular diseases can be initiated by mutations associated with blood cancer (DNMT3A, JAK2, ASXL1, and TET2)." (PMID 37726289, 2023). "Mutations in the DNMT3A, ASXL1, and TET2 genes can contribute to the development of blood cancer, and are frequently found in MDS and AML patients." (PMID 37726289, 2023). "Somatic mutations in DNMT3A are commonly identified as clonal hematopoiesis of indeterminate potential (CHIP) in healthy elderly adults without blood cancers and has been associated with cardiovascular events." (PMID 40287867, 2025). "Although cumbersome, this approach led to the successful introduction of clinically relevant mutations in a variety of genes, including DNA methyltransferase 3 alpha (Dnmt3a) and tet methylcytosine dioxygenase 2 (Tet2), within HSPC, and their introduction to mice to establish blood cancer models." (PMID 34395722, 2021). "In case of DNMT3A and DNMT3B, they were found out to be overexpressed in AML patients but their expression levels were not positively correlated with blood cancer stage nor poor prognosis of AML patients." (PMID 37573395, 2023).
neurodevelopmental disorder (6 papers, 2017 to 2025). A behavioral and cognitive disorder with onset during the developmental period that involves impaired or aberrant development of intellectual, motor, or social functions. "DNMT3A loss causes widespread transcriptional alterations and severe impairment of neuronal functions, and DNMT3A haploinsufficiency in the brain leads to neurodevelopmental disorders involved in growth and behavioral alterations." (PMID 35337381, 2022). "DNMT3A maintains and establishes DNA methylation marks, and previous research reveals co-occurring DNMT3A deficits and global DNA hypomethylation in neurodevelopmental disorder-related brain regions of first-generation DNE mice." (PMID 32138755, 2020).
benign tumors (4 papers, 2012 to 2023). "Of the mucious tumors, the expression of DNMT3a, DNMT3b, and DNMT1 was not different between malignant and benign tumors." (PMID 22768205, 2012).
cardiac disease (4 papers, 2023 to 2025). "Since in murine models of cardiac disease Tet2- and Dnmt3A-loss of function activated the inflammasome complex and promoted fibrosis development, it is conceivable that Dnmt3A or Tet2-CHIP-driver mutations contributed to the development of AVS." (PMID 40278194, 2025). "The direct effects of DNMT3A on the activation of T cells observed in the in vitro studies may, however, be particularly relevant in cardiac disease, given that T cells, specifically Th17 cells, are known to aggravate heart failure." (PMID 39196061, 2023).
kidney disease (4 papers, 2022 to 2024). "In line with this, the newly developed clonal hematopoiesis risk score, which stratifies the risk of CHIP progression to myeloid cancer and of developing CHIP-associated comorbidities including cardiovascular and kidney disease, accords more points for non-DNMT3A-CHIP compared to DNMT3A-CHIP38." (PMID 38454125, 2024). "Human kidney disease risk loci were enriched in fetal regulatory regions (enhancers) that were decommissioned by DNMT3A/3B and were no longer active in adult kidneys." (PMID 37928907, 2023). "Genetic and epigenetic (DNMT3A/3B) factors may converge in the same genetic region, resulting in the development of kidney disease." (PMID 37928907, 2023).
genetic diseases (3 papers, 2021 to 2024). "Besides these variants, the ExAC dataset contains 19 DNMT3A missense SNVs with some evidence of somatic origin, which are currently not described in relation to Mendelian diseases." (PMID 34906245, 2021).
adenocarcinoma (2 papers, 2018 to 2022). A common cancer characterized by the presence of malignant glandular cells. "Subgroup analysis of CRC patient after 3 months of FP therapy showed that DNMT3A expression level was significantly high in patients with adenocarcinoma type of tumors and high CA19.9 level." (PMID 30405408, 2018). "The expression of the pluripotency genes OSKM, the adenocarcinoma marker NKX2-1, the lung surfactant proteins SFTP, the myofibroblast marker MYH and DNMT3A/3B was analyzed with qRT-PCR and the presence of the myofibroblast markers vimentin and α-SMA with immunofluorescence." (PMID 35081981, 2022).
metabolic disease (2 papers, 2022 to 2025). A congenital disorder (due to inherited enzyme abnormality) or acquired (due to failure of a metabolically important organ) disorder resulting from an abnormal metabolic process. "The constitutive reduced DNMT3A in TBRS patients creates a domino effect leading to the development of marked inflammatory obesity and metabolic disease." (PMID 35635747, 2022).
neurodegenerative disease (2 papers, 2019 to 2023). A disorder of the central nervous system characterized by gradual and progressive loss of neural tissue and neurologic function. "In addition, plasma samples from patients with neurodegenerative diseases and senile cerebrovascular disease showed significant reductions in both global methylation and hydroxymethylation levels, as well as the mRNA levels of DNA methyltransferase 3 alpha (DNMT3α)." (PMID 40040784, 2023).
bacterial infection (1 paper, 2021). "Therefore, further investigations are needed to determine whether complementary mechanisms mediated by Dnmt3a occur in Dnmt3b deficient cells during bacterial infection." (PMID 33793661, 2021).
brain disorder (1 paper, 2020). A disease affecting the brain or part of the brain. "All these results suggest that the combination of the measurement of global DNA methylation and DNMT3a expression, used in combination with other routine clinical proofs, might represent a novel biomarker for age-related brain disorders in specialized settings." (PMID 32210102, 2020).
endocrine tumors (1 paper, 2016). "To determine if inactivation of menin increased the other three DNA methyltransferases (DNMT2, DNMT3a, and DNMT3b), we measured mRNA expression levels in the endocrine tumors from MEN1 patient samples and Men1 KO mouse models, and demonstrated no significant increase in DNMT2, DNMT3a, and DNMT3b." (PMID 26871472, 2016).
peripheral neuropathy (1 paper, 2019). A disorder affecting the peripheral nervous system. "The relevance of the DNMT3a isoform has also been confirmed by the observation that peripheral neuropathy evokes up-regulation of the DNMT3a enzyme in dorsal root ganglia (DRG) neurons, whereas DNMT3a knockdown attenuates neuropathic pain signs." (PMID 31426473, 2019).
DNMT3A also shares sentences with these, for which no sentence is quoted: autism (9 papers); Sotos syndrome (8); Hodgkins lymphoma (6); oral squamous cell carcinoma (3); T-cell acute lymphoblastic leukaemia (3); Thrombocytopenia (3); age-related macular degeneration (2); Anophthalmia (2); aplastic anemia (2); Arthritis (2); B-cell acute lymphoblastic leukemia (2); bipolar disorder (2); chronic hepatitis (2); chronic lymphoid leukemia (2); connective tissue disorder (2); Hydrocephalus (2); hydronephrosis (2); intervertebral disc degeneration (2); juvenile myelomonocytic leukemia (2); lung squamous cell carcinoma (2); Macrocephaly (2); myeloid sarcoma (2); neutropenia (2); psychosis (2); refractory anemia (2); serous ovarian cancer (2); small cell lung carcinoma (2); status epilepticus (2); testicular germ cell tumours (2); thymic carcinoma (2).
A further 120 diseases each share a sentence with DNMT3A in 2 papers or fewer.